IL6 (interleukin 6)
Diseases named in the same sentence as IL6 in open-access papers (continued):
Sharing a sentence is not in itself a finding about the gene and the disease.
infection (continued). "Although there were no typical symptoms after infection, the expression of proinflammatory cytokines IL-1β, IL-6 and IL-8 were significantly induced at 5 dpi in lungs and at 7 dpi in spleen, and at the same time, the expression of anti-inflammatory cytokine IL-10 was also induced." (PMID 31992193, 2020). "Interestingly, in infected cultures IL-6 and TNFα levels did not increase on day two while for IL-10 the upward trend was maintained at this time point and throughout the three days after infection with MCMV." (PMID 32455939, 2020). "Subsequently, we sought to examine the influence of Ss infection on the systemic levels of Type-1 (IFN-γ, TNF-α, and IL-2), Type-17 (IL-17A and IL-22), Type-2 (IL-4, IL-5, and IL-13), regulatory (IL-10) and pro-inflammatory cytokines (IL-1α, IL-1β, IL-6, IL-12, and GM-CSF) in INF and UN individuals." (PMID 33042134, 2020). "Consistently, the expression of Ifnb, Il6, or Isg56 and the production of IFN-β, IL-6, and TNF were significantly impaired in primary Rnf115−/− MLFs or BMDCs compared to the wild-type counterparts after infection with HSV-1, or transfection with dsDNA ligands or cGAMP." (PMID 33139700, 2020). "Considering the roles that IL-6 plays in immune responses and reactivation from latency, confirming whether RNA1.2 performs the same function during infection of other cell types, especially immune cells such as macrophages and dendritic cells, would be worthwhile." (PMID 32793512, 2020). "Neutralization of IL-6 during infection of WT animals did not change the hybrid Th1/Tfh phenotype." (PMID 32634740, 2020). "Furthermore, we also showed that cytokines such as IL-1β, IL-6, TNF-α, IL-8, and IL-10 may act as indicators of a lethal outcome at the endpoint of the infection process." (PMID 33553280, 2020). "In addition, it has been shown that infections by the H9N2 influenza virus strain, which originated from swine hosts, in BALB/c mice resulted in inflammation and injury in the lung with production of pro-inflammatory cytokines including TNFα, IL-1β and IL-6." (PMID 32709018, 2020). "Furthermore, B cells also produced IFN-α, IL-6, and IL-1 upon TMEV infection." (PMID 32727036, 2020). "Another possible limitation of this study is the borderline significance of difference in IL-6 levels between tested groups, which could reflect non-clinically evident infections." (PMID 32714087, 2020). "To reach this goal, we examined a dataset of DANCR knockdown (KD) in neuron progenitor cells and found downregulation of cytokines and the non-canonical pathway NFkB (IL-6 and NFKB2, p<0.05, FDR), indicating increased susceptibility to infection in differentiated neurons." (PMID 33163005, 2020). "However, although IL-6 also induces leptin production, leptin levels were not significantly altered after infection with Brucella abortus." (PMID 33071987, 2020). "Our data suggest that while IL-6 may still be a reliable marker for infection/inflammation in PTB and pPROM, it does not functionally contribute to the disruption of cellular homeostasis in the membranes." (PMID 32848846, 2020). "Intriguingly, the ΔCagPAI mutant was able to induce expression of IL-6 but failed to induce expression of TNFα after 1 h of infection, whereas Brefeldin A treatment resulted in decreased IL-6 but stable TNFα mRNA levels upon infection with the wt strain." (PMID 33023610, 2020). "Moreover, in the absence of IL-6, IL-10 secretion was slightly enhanced only upon infection with lower bacterial loads while IL-6 KO macrophages stimulated with LPS showed no alterations in IL-10 secretion when compared to wild-type cells." (PMID 33322581, 2020). "Moreover, in open wounds, SDSE wild-type but not ΔhylD mutant resided on day 2 post-infection, resulting in infiltration of neutrophils and increase of serum IL-6 level." (PMID 33072013, 2020). "Furthermore, the upregulation of IL-6 following apical or basolateral E-30 infection was observed with the q-PCR but was not significant." (PMID 32872518, 2020).
infection (continued). "Previous studies have highlighted that low-grade infections might not result in elevated CRP or IL-6; however, due to limited numbers these findings should be evaluated for specific organism in future studies." (PMID 32927683, 2020). "We also assessed the role of IL6, a lymphokine associated with CSFV infection, and presented a mechanistic hypothesis that CSFV Shimen up-regulate AIF1 expression to induce up-expressed IL6, to help us understand AIF1-related inflammation in CSFV Shimen infection." (PMID 32110485, 2020). "Infection may be followed by the upregulation of viral RNA sensors, IFN-stimulated genes (IP-10, ISG15, OAS1, OAS2, Mx2), and different cytokines (interleukin-6 (IL6), IL8, monocyte chemoattractant protein-1 (MCP1))." (PMID 32664675, 2020). "Although the exact pathogenesis of CD is unclear, studies have indicated that the occurrence of CD may be related to the infection of human herpes virus-8 (HHV-8) or human immunodeficiency virus (HIV), immune dysfunction and overproduction of interleukin-6 (IL-6)." (PMID 33796182, 2020). "In addition, the patients infected with TM have previously been reported to have higher TNF-α, IL-1β, IL-12, and IL-10 levels in vivo, and the infection of TM enabled the enhancement of the production of cytokines such as TNF-α, IL-1β, IL-6, and IL-12 by stimulating macrophages in vitro." (PMID 33488545, 2020). "Moreover, monocytes and neutrophils are recruited to the site of infection by the IL-17 released by T helper cells, which further exacerbates the condition via release of downstream cytokines and chemokines, such as TNFα, MCP-1, IL-6, IL-1, IL-8 and IL-21." (PMID 32781571, 2020). "Western blotting analysis revealed differences in AIF1 and IL6 protein expression levels between CSFV-infected and uninfected control cells, which demonstrated that AIF1 and IL6 levels increased significantly in the first 48 h after infection relative to the levels at the 0 time point." (PMID 32110485, 2020). "Interestingly, anti-CD20 injection before the infection did not affect the serum IL-6 concentration since that IL-6 values were similar at 15 and 20 dpi." (PMID 32398312, 2020). "Similarly, in spleens from LCMV-infected RAG1 KO mice, there were no significant changes for TNF, IL-1β and IL-6 mRNAs post infection." (PMID 32310998, 2020). "Considering the relatively low expression level of IL6 in MEFs, BHK21 cells with undetectable endogenous IL16 were overexpressed with IL16-expressing plasmid with Flag tag or vector alone for 24 hr, followed by MHV68 infection with a high MOI of 5 or a low MOI of 0.05." (PMID 32735617, 2020). "In response to HPIAVs infection, such as infection by H5N1, which induces deregulated pro-inflammatory cytokine expression, inhibition of c-Jun, a target molecule of JNK and a component of AP-1, has been shown to suppress the expression of IFNβ and other cytokines, including IL-6 and TNFα." (PMID 32709018, 2020). "Actually, IL-6 is a marker of nonspecific pathogen infection or inflammation." (PMID 32089650, 2020). "Maternal infection during pregnancy was associated with a 7% lower CRP level (among offspring compared with offspring born to women without an infection (95% CI, − 17,5%) and similarly an 8% lower level of IL-6 (95% CI, − 15, 1%), and a 9% lower level of IL-10 (95% CI, − 23,20%)." (PMID 30923624, 2019). "MEKi did not modulate production of IL-1β or IL-6 following RV2 or RSVA2 infection." (PMID 31319869, 2019). "On average 5.6 times more IL1B mRNA (p < 0.001), 5.2 times more IL6 mRNA (p < 0.001), 4.3 times more TNF mRNA (p < 0.001) and 48.5 times more IFNG mRNA (p < 0.001) were produced by bMDM pre-treated with NTC siRNA in response to AF2122/97 infection than G18 infection." (PMID 31527895, 2019).
infection (continued). "-Downregulation of IL-6, IL-1β, and TNF-α -Cotreatment with 0.005 mg/g epinecidin-1 decreased the mortality rate upon infection. - 7 days after P. aeruginosa ATCC 19660 and P. aeruginosa R infection, the survival rate is 88.4% - All untreated mice died within 72 h of infection." (PMID 31824449, 2019). "Moreover, microarray assay in combination with CRNG interference and overexpression showed that the differential genes such as ANPEP, KITLG, STAT5A, FOXP3, miR-451, IL-2, IL-10, IL-6, and TNF-α are mainly involved in viral and pathogens infection and the immune-inflammatory responses in PK-15 cells." (PMID 31178726, 2019). "IL-6 can potentiate the antiviral effect of interferon alpha, and exogenous IL-8 can inhibit HIV replication, raising the possibility that these cytokines could confer additional antiviral effects that contribute to abortive VA1 infection." (PMID 31289185, 2019). "Interestingly, in response to Mtb WCL stimulation, TNFα, IL6, IL12p40, and IL1β were produced to a significantly higher extent by BAL cells of cynomolgus macaques already prior to infection, concordant to the pro-inflammatory profile of circulating monocytes in cynomolgus macaques." (PMID 31736945, 2019). "During S. Typhimurium infection of colonic epithelial cells, the NF-κB target genes IL6, IL8, and TNFA are induced, corresponding with enhanced ubiquitination of IκBα as well as β-catenin degradation which demonstrates the reciprocal activation of these two pathways by infection." (PMID 31681283, 2019). "Interestingly, a reverse trend of dynamic change was found between two pro-inflammatory cytokines IL-6 and IL-8 in both secondary infection and non-secondary infection groups." (PMID 31627725, 2019). "The action of IL10 appears to be solely responsible for the suppression of IL1B and IL6 production during G18 infection, thus supporting our hypothesis that IL10 induced during G18 infection is dampening down some of the transcriptional response of bMDM to infection." (PMID 31527895, 2019). "Moreover, IL-6, IL-10, TNF-α and IFN-γ mRNA were found to be significantly increased in the trigeminal ganglia (TG) of 2-week-old piglets infected with virulent PRV strain NIA3 at 2 days post-infection." (PMID 31675371, 2019). "The finding that infection of hPCLS with Y. pestis lacking Pla results in increased secretion of IL-8, IL-6, and TNF-α suggests that Pla may play an early immunosuppressive role in the lung by facilitating efficient T3S of alveolar macrophages." (PMID 31085709, 2019). "In addition, we did not observe any secretion of IL-2, IL-10, IL-13, and IL-6 during an AIC infection." (PMID 31801841, 2019). "Similarly, NTHi infection increased IL-6 production (p < 0.001) but this was not altered by prior PM10 exposure (p = 0.13)." (PMID 31344807, 2019). "Moreover, the inflammatory response of BE was only due to HRV-16 infection since UV-inactivated HRV-16 did not trigger IL-6 production." (PMID 31969885, 2019). "During the course of infection, IL-6, a well-known pro-inflammatory mediator with rapid concentration dynamics, showed some inverse correlation to LPC levels, findings that may relate to that both LPC and IL-6 are involved in regulation of immune cells." (PMID 31063483, 2019). "Additionally, serum ESR, CRP, and IL-6 had no benefit in predicting persisting infection before second-stage prostheses implantation." (PMID 31159792, 2019). "Unlike CRP, IL-6 can also help to distinguish infection from fever of unknown origin in pediatric practice." (PMID 31795299, 2019). "Although the mechanism leading to this infection is not well understood, the hypothesis is that the blood-brain barrier permeability is modified due to the presence, in blood and/or in CNS, of inflammatory mediators such as IL1, IL6 and TNFA." (PMID 30908482, 2019).
infection (continued). "Three days post-infection, the E. coli challenge significantly increased the expression of nuclear factor-κB (NF-κB), peroxisome proliferator-activated receptor-γ (PPAR-γ), toll-like receptor 4 (TLR4), IL-1β, and IL-6 (P < 0.05) and tended to increase the expression of TNF-α (P = 0.052)." (PMID 29948799, 2019). "This is consistent with previous our and other studies demonstrating that immunized mice showing higher efficacy (lower lung viral titers) show lower proinflammatory cytokines (IFN-γ and IL-6) in the lungs of mice than non-immunized mice upon infection with influenza virus." (PMID 31246961, 2019). "Twenty-four hours after infection, we assessed inflammatory responses of the macrophages by measuring the levels of cytokines, including granulocyte/macrophage colony-stimulating factor (GM-CSF), IFN-γ, interleukin (IL)-2, IL-4, IL-6, IL-8, IL-10 and TNF-α, secreted in the culture supernatant." (PMID 29712918, 2018). "Levels of IL-6 were not altered by infection with N315 αHL+." (PMID 30705678, 2018). "In addition, elderly LPS/IFN-γ-MoDCs may have (i) a reduced ability to recruit neutrophils and monocytes to a site of infection, due to reduced IL-8 and MCP-1; and (ii) a decreased ability to stimulate Th2 and Th17 responses, due to reduced IL-6 secretion." (PMID 29652910, 2018). "However, IL-6 alone does not induce as high of an infection level as EC- or LEC- (and unpublished data)." (PMID 30285810, 2018). "Expression of an array of cytokines (CSF3 [G-CSF], IFNγ, IL-1β, IL-6, IL-22, IL-17A, and IL-10), chemokines (CCL20, CXCL2 and CXCL9) and receptors (CD40) known to be involved in the regulation of S. pneumoniae inflammatory response was measured at 0, 6, 24, and 48 h post-infection." (PMID 30333823, 2018). "The increased expression of IL-6 and IL-23 in stat3fl/fllysm cre APCs was not restricted to the infection with attenuated or virulent mycobacteria since, it was observed after incubating mutant APCs with different TLR agonists or bacterial lysates, confirming previous data." (PMID 29338039, 2018). "Notably, infection of C. glabrata, unlike that of S. cerevisiae and C. albicans, is known to induce reduced production of IL-6, IL-8, TNFα, IL-1β, and IFN-γ in human monocyte-derived macrophages." (PMID 29491142, 2018). "During infection of primary human cortical astrocytes, for example, cytomegalovirus induces release of chemoattractant protein-1 and IL-8, while human immunodeficiency virus (HIV) induces release of IL-6 and Zika virus induces release of CXCL-10, IL-6, IL-8, IL-12, and RANTES." (PMID 30442152, 2018). "In cases of preterm labor the cervical changes like cervical softening associated with painless dilatation, and shortening is explained by increased synthesis of interleukin (IL)-6 amd IL-8 and prostaglandin synthesis, and monocyte chemotactic protein I in absence of infection." (PMID 29670041, 2018). "Although it decreased the influenza M gene (encoding the M protein related to inflammatory response and virus replication), IL-6, and IFNβ in A549 cells prior to and post-infection with H9N2 influenza, the authors found that it did not affect virus replication in vitro and in vivo." (PMID 30115864, 2018). "The activation state of signaling pathways of two pro-inflammatory cytokines, IL-6 and IL-8, as well as induction of the p38 MAPK pathway, suggests potential mechanisms responsible for the highest virulence of BOR strain observed in the experimental infection study." (PMID 29882085, 2018). "We speculate that these differences are at the basis of the cytoprotective nature of the IFNα response as opposed to oncolysis in the absence of productive infection, induced by IL-6." (PMID 29441069, 2018).
infection (continued). "Less than 1 U/mL of IL-6 were detected in both infection groups (data not shown)." (PMID 29343690, 2018). "IL-17 induces the expression of pro-inflammatory cytokines and chemokines, such as G-CSF, IL-6 and IL-8, promoting recruitment of neutrophils and granuloma formation, as well as the expression of other chemokines, including CXCL10 that recruits IFNγ producing cells to the site of infection." (PMID 29554138, 2018). "Etanercept has been shown to protect against the in vivo lethal infection of mice with a highly virulent, mouse-adapted IAV strain, with observations made of an increased survival rate with decreased morbidity, expression of the proinflammatory cytokine IL-6, lung injury, and edema." (PMID 30042762, 2018). "By analyzing L. major BNI infection in the liver, we found a comparatively low iNOS expression in B6.TNF−/− macrophages and an accumulation of a myeloid population that exhibited an alternatively activated-like macrophage phenotype, with high expression of Arg-1, CD206 and IL-6." (PMID 29403488, 2018). "Furthermore, increase in pro-inflammatory plasmatic cytokines, IL-6, IFN-γ, and TNF-α together with the presence of activated macrophage in both blood and spleen could help in resolution of infection with B. microti." (PMID 29445365, 2018). "Thus, absence of classical IL-6 signaling in myeloid cells did not impair but rather enhance the T-cell response to infection." (PMID 30169526, 2018). "HSV-2 + Cc-Griffithsin also produced significantly more IL-6 at 4 hours post-infection compared to virus alone, although this was about 20% less IL-6 than what was produced by HSV-2 + Cc-A1AT, and not statistically significant when compared to HSV-2 + Cc-Control." (PMID 29434285, 2018). "This suggests that IL-6 may be necessary but not sufficient in inducing high level of infection, or there are additional factors involved in the stimulation." (PMID 30285810, 2018). "Similarly, IL-6 and IL-18 cytokines seem to have no role on infection outcome or to be markers of active disease or asymptomatic infection." (PMID 30237985, 2018). "Infection of MDMs with MERS-CoV appreciably induced the secretion of antiviral cytokines (IFN-α2, IFN-γ, and IL-12p40), moderately or appreciably up-regulated proinflammatory cytokines (TNF-α, IL-6), and variably upregulated inflammatory chemokines (MIP-1α, IP-10, RANTES, IL-8)." (PMID 29566060, 2018). "Indeed, phagocytosis of infected apoptotic cells could trigger TLR activation and lead to IL-6 and TGF-β production that induce the development of infection-specific as well as self-reactive TH17 cells, linking infection to autoimmunity." (PMID 30459758, 2018). "The hepatic levels of TNF, IL-6, IL-1β, and IL-12p70 did not change significantly upon infection." (PMID 29568732, 2018). "Infection with EV 71 can activate the c-Jun NH2-terminal kinase (JNK) and p38 mitogen-activated protein kinase (MAPK) signaling pathways, thereby contributing to increased viral replication and secretion of cytokines such as interleukin (IL)-2, IL-6, IL-10, and tumor necrosis factor (TNF)-α." (PMID 30545363, 2018). "Four weeks post-infection, a real-time PCR analysis of inflammatory gene expression revealed that purified macrophages from infected WT mice exhibited enhanced IL-10, Arg-1, MCP-1, RELMa, and IL-6 but reduced TNF-α, IL-12, and iNOS mRNA levels, which exhibited an M2 dominant- polarized phenotype." (PMID 30589840, 2018). "How might viruses benefit from maintaining the expression of IL-6 and GADD45B during infection?" (PMID 28841715, 2017). "None of the virus mono-infections significantly altered the levels of IL-6 and IL-8." (PMID 28644900, 2017). "In addition, germline deletion results in the absence of IL-6 throughout development while αIL-6 or αIL-6R antibodies remove signalling only at the point of infection." (PMID 28953978, 2017).